GPNMB (glycoprotein nmb)
Diseases named in the same sentence as GPNMB in open-access papers (continued):
Sharing a sentence is not in itself a finding about the gene and the disease.
Hepatic fibrosis (7 papers, 2015 to 2025). The presence of excessive fibrous connective tissue in the liver. "In addition, GPNMB transgenic mice were protected from liver fibrosis under choline-deficient, L-amino acid-defined (CDAA) diet." (PMID 29799853, 2018). "A subset of macrophages expressing SPP1, GPNMB, FABP5, and CD63 have also recently been identified in pulmonary and hepatic fibrosis associated with scar formation." (PMID 38902328, 2024). "Serum GPNMB levels showed the tendency to increase with the progression of liver fibrosis (stage 1; n = 27, 18.14 ± 7.99 ng/ml, stage 2; n = 9, 19.90 ± 8.42 ng/ml, stage 3; n = 13, 15.64 ± 8.29 ng/ml, stage 4; n = 11, 26.92 ± 10.76 ng/ml)." (PMID 26581806, 2015). "Additionally, it has been found that serum gpNMB concentrations in other clinical contexts correlated with the severity of liver fibrosis." (PMID 41152894, 2025). "Similarly, in our study, gpNMB concentrations of patients with liver disease, including liver fibrosis and liver cirrhosis, were statistically greater than in those patients without manifest liver disease." (PMID 41152894, 2025). "Finally, current evidence suggests a protective role for GPNMB in hepatic fibrosis and a potential for soluble GPNMB." (PMID 29799853, 2018). "Since serum GPNMB levels were higher, and platelet counts and ALT levels were lower in stage 4, we performed multivariate logistic regression analysis to assess the parameters as a risk for liver fibrosis." (PMID 26581806, 2015). "The post-interventional dynamics of physiologically relevant adipokines and hepatokines (ANGPTL4, CCL5, GDF15, GPNMB, IGFBP6), as well as their correlation with fat mass reduction and improvement of liver fibrosis, were analyzed." (PMID 36430499, 2022). "Combined with our own data in liver fibrosis and studies in other organs, we were able to further scrutinize these data to identify a cohort of highly expressed ECM proteins amenable to assay in patient serum samples, including OPN, VIM, SPARC, GPNMB and FN1." (PMID 30559459, 2018). "Although serum GPNMB well-correlated with degree of liver fibrosis, it did not demonstrate significant correlations with NAFLD activity score (NAS) and necroinflammatory grading system, which represent the degrees of steatosis, ballooning and inflammation." (PMID 26581806, 2015). "This strongly predictive character for hepatic fibrosis was exclusively observed for GDF15 but not for ANGPTL4, CCL5, GPNMB, and IGFBP6." (PMID 36430499, 2022).
non-alcoholic steatohepatitis (7 papers, 2015 to 2026). "It has been reported that serum gpNMB concentrations were higher in patients with nonalcoholic steatohepatitis compared with simple steatosis." (PMID 41152894, 2025). "In the patients with non-alcoholic steatohepatitis, serum soluble GPNMB concentrations were higher compared with the patients with simple steatosis." (PMID 26581806, 2015). "Importantly, patients with metabolic dysfunction-associated steatohepatitis (MASH) and diabetes who received anti-diabetic treatment showed a reduction in hepatic GPNMB expression." (PMID 41800647, 2026).
vitiligo (7 papers, 2020 to 2025). Generalized well circumscribed patches of leukoderma that are generally distributed over symmetric body locations and is due to autoimmune destruction of melanocytes. "Clinically, suppressed GPNMB expression correlates with susceptibility to chronic inflammatory conditions including periodontitis, nephritis, and vitiligo." (PMID 41180454, 2025). "Then, GPNMB was knocked down to mimic vitiligo KCs to investigate the role of GPNMB and its underlying mechanisms in cell susceptibility to H2O2 treatment." (PMID 39947468, 2025). "Evidence that GPNMB protects melanocytes from cytotoxicity induced by oxidative stress further argues for a role in the vitiligo pathogenic mechanism." (PMID 38473275, 2024). "We have previously shown that IFN-γ and IL-17A, which have also been reported as possible causative cytokines in vitiligo development, inhibited GPNMB expression." (PMID 34639184, 2021). "We previously showed that the possible causative cytokines in vitiligo development inhibited GPNMB expression in primary keratinocytes in vitro." (PMID 34639184, 2021). "Our previous report suggested that the expression of GPNMB was abrogated in the vitiligo epidermis, suggesting its pathogenic involvement." (PMID 34638746, 2021). "To account for the possibility that the loss of GPNMB signals in vitiligo epidermal keratinocytes stems from enzymatic cleavage or the secretion of cell-associated GPNMB, we examined the capacity of keratinocytes to release soluble GPNMB (sGPNMB)." (PMID 32188902, 2020). "On the contrary, GPNMB signals remained positive in the lesional epidermis of nevus depigmentosus skins, indicating that the loss of epidermal GPNMB was unique to vitiligo depigmentation." (PMID 32188902, 2020). "IFN-γ and IL-17A, two cytokines with possible causal roles in vitiligo development, inhibited GPNMB expression in vitro." (PMID 32188902, 2020). "Alternatively, the disappearance of keratinocyte-GPNMB in vitiligo lesions might be induced via the loss of unknown soluble factors which are released from healthy melanocytes to maintain the keratinocyte-GPNMB." (PMID 32188902, 2020). "Moreover, we provided evidences that IFN-γ and IL-17A, two cytokines with possible causal roles in vitiligo development, inhibited GPNMB expression in vitro." (PMID 32188902, 2020). "GPNMB is expressed in the basal epidermal layer of healthy skin but is lost specifically in vitiligo lesions." (PMID 39947468, 2025). "The significant decrease in DKK1 production by GPNMB knockdown suggests that GPNMB is a key molecule regulating the WNT/β-catenin signaling pathway in vitiligo KCs." (PMID 39947468, 2025). "Further quantitative measurement of phosphorylated ASK2/total ASK2 levels is required for the involvement of the ASK2/TXN/TXNIP pathway in decreased KC GPNMB expression and vitiligo pathogenesis." (PMID 39947468, 2025). "Taken together, these results suggest that the decreased expression of KC GPNMB in vitiligo lesions triggers increased sensitivity to H2O2-induced oxidative stress and decreased signaling in the WNT/β-catenin axis." (PMID 39947468, 2025). "The findings clarify the role of GPNMB in KCs and provide novel insights into the pathophysiology of vitiligo for clinical applications." (PMID 39947468, 2025). "This study aimed to determine the role of KC GPNMB in normal and vitiligo epidermis and demonstrated that GPNMB plays a protective role against H2O2-induced oxidative stress due to its extracellular domain." (PMID 39947468, 2025). "This study was designed to assess the role of decreased epidermal GPNMB expression in vitiligo pathogenesis with a focus on melanocytes." (PMID 34639184, 2021). "Oxidative stress is one of the possible pathogenetic factors of vitiligo, and decreasing GPNMB expression in vitiligo is reasonable." (PMID 34639184, 2021). "In this study, we demonstrated that GPNMB expression was also decreased in rhododendrol-induced leukoderma, as seen in vitiligo." (PMID 34639184, 2021).
vitiligo (continued). "We have also demonstrated that the disappearance of keratinocyte-GPNMB in vitiligo lesions is characteristic of vitiligo depigmentation, because the GPNMB signals remained positive in the lesional epidermis of nevus depigmentosus skins." (PMID 32188902, 2020). "Next, we investigated the expression of GPNMB in the epidermis of healthy skins and in depigmented skins from vitiligo and nevus depigmentosus patients." (PMID 32188902, 2020). "The roles of GPNMB in vitiligo and in healthy skin will be better elucidated by further in vivo and in vitro investigations into the functions and regulatory roles of GPNMB in keratinocytes and melanocytes." (PMID 32188902, 2020). "We were impressed, therefore, to find that both of vitiligo-associated IFN-γ and IL-17A downregulated keratinocyte-GPNMB." (PMID 32188902, 2020). "Intriguingly, GPNMB signals were abolished in the basal layer keratinocytes of vitiligo lesions, whereas the signals in prelesional regions were maintained at the same levels as those in healthy skin." (PMID 32188902, 2020). "In addition, decreased GPNMB expression was observed in the epidermis of lesional skin of patients with vitiligo." (PMID 34639184, 2021). "It suggests that a decreased expression of GPNMB in the epidermis may be involved in the pathogenesis of vitiligo, and that approaches that reverse GPNMB expression in the epidermis may be effective in vitiligo treatments." (PMID 34639184, 2021). "In vitiligo epidermis, GPNMB expression is diminished in basal keratinocytes." (PMID 34639184, 2021). "Furthermore, IFN-γ, IL-17A, and oxidative stress dampened the GPNMB expression in vitiligo keratinocytes." (PMID 34639184, 2021). "Our results suggest that GPNMB might provide novel insights into the mechanisms related to the pathogenesis of vitiligo and leukoderma." (PMID 34639184, 2021). "We cannot exclude the possibility that unknown vitiligo-related factors accelerate GPNMB shedding to produce sGPNMB, thereby affecting the vitiligo pathophysiology by modulating the functions of keratinocytes and/or melanocytes." (PMID 32188902, 2020). "In our next experiments we sought to explain the disappearance of GPNMB signals in vitiligo lesional epidermis by examining how several cytokines and chemokines potentially involved in vitiligo pathophysiology affected GPNMB expression and sGPNMB production in NHEKs." (PMID 32188902, 2020). "We found that keratinocytes in the basal layer of the vitiligo lesion lost the GPNMB signals although perilesional keratinocytes retained the positive signals, suggesting that GPNMB disappearance from keratinocytes is closely correlated with the loss of melanocytes." (PMID 32188902, 2020). "However, the lesional epidermis of nevus depigmentosus skins showed positive signals in spite of the loss of melanocytes, indicating that the disappearance of epidermal GPNMB is specific to vitiligo depigmentation." (PMID 32188902, 2020). "However, the precise physiological function of GPNMB in NHEKs, and its role in vitiligo, remain unclear." (PMID 39947468, 2025). "Therefore, IFN-γ-mediated decrease in KC GPNMB expression may partially explain the pathogenesis of vitiligo." (PMID 39947468, 2025). "Therefore, reduced GPNMB expression in vitiligo lesions may play an important role in their pathophysiology, particularly in the sensitivity of KCs to oxidative stress." (PMID 39947468, 2025). "Interestingly, lack of GPNMB expression is a specific characteristic of depigmented vitiligo skin." (PMID 38473275, 2024). "Therefore, a combination of oxidative stress and these cytokines could suppress GPNMB expression in epidermal keratinocytes in patients with vitiligo." (PMID 34639184, 2021). "IFN-γ and IL-17A exerted no influence on the shedding of cell-associated GPNMB, whereas both decreased the GPNMB expression itself, possibly loosening the interaction between the keratinocytes and melanocytes to form the floating melanocytes in vitiligo." (PMID 32188902, 2020).
vitiligo (continued). "Previously, we found that glycoprotein nonmetastatic melanoma protein B (GPNMB) is specifically lost in the basal epidermal layer of vitiligo lesions and downregulated by IFN-γ in normal human epidermal keratinocytes (KCs) (NHEKs)." (PMID 39947468, 2025). "Recently, we demonstrated that GPNMB was expressed in the basal keratinocytes of normal skin and nevus depigmentosus skin, but not in vitiligo skin." (PMID 34639184, 2021). "We also showed that GPNMB was expressed in healthy skin epidermis and in nevus depigmentosus skin, but it was absent in the lesional epidermis of vitiligo patients." (PMID 32188902, 2020). "Histological staining showed that GPNMB was expressed in the basal layer of normal skins but completely absent in vitiligo skins." (PMID 32188902, 2020). "The normal expression of GPNMB in nevus depigmentosus skin suggested that lack of GPNMB is characteristic of vitiligo lesional skins." (PMID 32188902, 2020). "Moreover, GPNMB is substantially expressed in cultured NHEKs under low Ca2+ conditions (0.07 mM) and, notably, downregulated by IFN-γ, which plays a critical role in vitiligo onset and maintenance." (PMID 39947468, 2025).
breast tumor (6 papers, 2010 to 2023). "This is consistent with our previous observations that GPNMB/OA is also overexpressed in human breast tumors, and suggests that GPNMB/OA may be functionally implicated in regulating tumor growth in addition to promoting invasion and metastasis." (PMID 20711474, 2010). "Through enhancing PI3K/AKT/mTOR pathway signaling and β‐catenin activity, GPNMB promotes breast tumor initiation and growth mediated by Wnt‐1 signaling." (PMID 38140790, 2023). "Recently, gpNMB was found to augment WNT-1-mediated breast tumor initiation and growth by enhancing PI3K/AKT/mTOR pathway signaling and B catenin activity." (PMID 34016993, 2021). "Elevated expression of GPNMB in all cancer and its remarkable role in breast tumor progression has proven it to be a potential therapeutic target." (PMID 30760814, 2019). "A panel of PDX breast tumor tissues were screened for mRNA expression of gpNMB at different passages." (PMID 29262642, 2017). "Given the utility of GPNMB/OA expression as a prognostic indicator of recurrence and its potential as a therapeutic target in human breast tumors, we aimed to investigate the functional role of GPNMB/OA in the primary breast tumor microenvironment." (PMID 20711474, 2010). "Together, these observations support the hypothesis that shed GPNMB/OA augments breast tumor angiogenesis by directly stimulating endothelial migration." (PMID 20711474, 2010). "GPNMB increases the expression of neuropilin-1 (NRP-1) that forms a complex with VEGFR2 to enhance tumor cell-intrinsic VEGF signaling and primary breast tumor growth." (PMID 27304911, 2016). "Importantly, we restricted these analysis to examining GPNMB/OA expression in the tumor epithelium of high and low MVD primary breast tumors; therefore, it remains to be determined whether GPNMB/OA expression in the tumor stroma is also associated with enhanced angiogenesis." (PMID 20711474, 2010).
Cerebral ischemia (6 papers, 2016 to 2023). Restriction of arterial blood supply to the brain associated with insufficient oxygenation to support the metabolic requirements of the tissue. "A previous study stated GPNMB as a novel neuroprotective factor in cerebral ischemia–reperfusion injury." (PMID 36820063, 2023). "GPNMB has been described to have neuroprotective, reparative, or anti-inflammatory actions in neurodegenerative disorders and cerebral ischemia-reperfusion injury." (PMID 37006485, 2023). "Similarly, GPNMB expression was also found to be increased in animal models of cerebral ischemia injury." (PMID 37786733, 2022).
heart failure (6 papers, 2016 to 2025). Inability of the heart to pump blood at an adequate rate to meet tissue metabolic requirements. "Increased levels of GPNMB in plasma have also been linked with a higher risk of cardiovascular diseases, particularly myocardial infarction and heart failure." (PMID 37047799, 2023). "Notably, GDF15 and GPNMB (patent publication number—WO2012072752 A1) have been proposed as diagnostic biomarkers of heart failure and were also up-regulated in our model system." (PMID 26537877, 2016). "We have identified GPNMB as a promising novel plasma biomarker for heart failure based on our preliminary data in two HF mouse models and in human samples." (PMID 30201759, 2018). "To confirm the protein levels of GPNMB in heart failure, we used two widely accepted modes of cardiac injury, isoproterenol (ISO) and transverse aortic constriction (TAC), to induce a heart failure-like state in mice." (PMID 30201759, 2018). "However, our experiments in mice, using matched littermate controls, supports our claim that GPNMB may be a useful independent heart failure biomarker." (PMID 30201759, 2018). "As observed in the ISO mice, there were significantly lower plasma GPNMB levels in patients with HF compared with non-HF controls (GPNMB 1.20 ± 0.26 ng/mL in control vs. 0.74 ± 0.40 ng/mL in heart failure, p-value < 0.0001)." (PMID 30201759, 2018).